TNF (tumor necrosis factor)
Diseases named in the same sentence as TNF in open-access papers (continued):
Sharing a sentence is not in itself a finding about the gene and the disease.
tumor (continued). "Top gene hits identified through both screens involved in for example TNFα signaling were CFLAR, MAPK1, RIPK1, TNFRSF1A, and ICAM1, highlighting their role in regulating tumor sensitivity to TNF-α-induced cell death." (PMID 37732732, 2023). "TNF-α, in a healthy state, is a crucial immunomodulator involved in hematopoiesis, innate immunity, dendritic cell maturation, bacterial infections, and tumor regression." (PMID 36771154, 2023). "To further evaluate the effector function of different CAR-T cells upon antigen-specific stimulation, we conducted a coculture assay to measure the release of cytokines (IFN-γ, TNF-α and IL-2) after incubation with tumor cells." (PMID 37777797, 2023). "Capsular polysaccharides (CPS) on the cell surface are also recognized by macrophage TLR-4 receptors and lead to production of TNF-α and subsequent inhibition of angiogenesis, disrupting tumor growth." (PMID 37514190, 2023). "RT plus anti-TIGIT combination therapy increased the number of CD8 + T cells and the percentage of IFNγ + TNFα + CD8 + T cells in tumor tissues and TdLNs in WT mice." (PMID 35794399, 2023). "Tumor necrosis factor (TNF) is a potent pro-inflammatory cytokine exerting both tumor-promoting and anti-cancer effects." (PMID 36653597, 2023). "The majority of DEGs were shared between cytokine blockade treatments, suggesting that TNFα, IL-1β, and IL-6 signaling converge on similar pathways in the tumor microenvironment." (PMID 37461742, 2023). "NK cells pre-exposed to tumor cells expressing MHC-I promote host extramedullary myelopoiesis, which is partly related to TNF-α secretion by tumor-experience NK cells." (PMID 38041084, 2023). "High serum levels of proinflammatory cytokines, such as interleukin (IL)-1, IL-6, IL-8, and TNF-α, are often related to tumor growth and poor clinical prognosis in cancer patients." (PMID 36793738, 2023). "The Th1 subset produces IFN-γ, TNF-α and IL-2, which regulate cellular immunity and play important roles in anti-tumor immune responses." (PMID 37880313, 2023). "They found that the rs1800629 genotype of TNF-α was more frequently found in more advanced stage tumours, and those with poorer survival." (PMID 36980727, 2023). "IL-10 is an anti-inflammatory cytokine that plays a crucial role in tumor killing and inhibits the production of IFNg, IL-2, IL-3, and TNFα." (PMID 37445686, 2023). "The activated TAMs in the residual tumor in turn produced more TNF-α and CCL2, resulting in enhanced inflammation." (PMID 36831664, 2023). "Among the eleven immunological markers examined, three (PD-L1, TNF-α, and IL-6) demonstrated a decline in the proportion of tumors with a high marker expression in late-stage compared to early stage tumor samples." (PMID 37444550, 2023). "The combined treatment led to a significant increase in ROS and TNF-α levels in glioma cells, an 8-fold reduction in tumour volume, and a 35% increase in the survival rate of mice." (PMID 37514054, 2023). "In lung tumors and the skin, a proportion of CD8+ TRM cells displaying strong CD49a and CD103 expression can produce Th1 cytokines, such as IFN-γ and TNF-α, and IL-17, suggesting a particular function in the control of tumor progression." (PMID 37545498, 2023). "Activated CD8+T cells destroy tumor cells by releasing massive granzyme, perforin as well as tumor necrosis factor (TNF)." (PMID 37007125, 2023). "In a mouse glioma model, the mRNA expression of IL‐β1 and TNF‐α in tumor cells was significantly increased by SR‐717@RGE‐HFn treatment." (PMID 36999977, 2023). "SPP significantly reduced TNF-α and IL-2 in tumor-bearing nude mice in our experiments, implying that SPP improves the serum inflammatory response in nude mice." (PMID 37538184, 2023). "In normal tissues, Se-PC promotes the synthesis of antioxidant enzymes and the immune response by the IL-6/TNF-α pathway against tumor proliferation and metastasis." (PMID 37994159, 2023).
tumor (continued). "The gut microbiota also induce TNF-α expression via tumor-associated natural bone marrow cells, mediating TNF-dependent early tumor necrosis." (PMID 37553473, 2023). "In comparison to the untreated or abscopal effect group, the mice presenting significant abscopal effect also elevated the proportion of CD4+ TNF-α+ T cells into the tumor." (PMID 37182153, 2023). "Immunophenotyping of the rechallenged LTS animals showed an increase in the percentage of CD8 T-cell population expressing pro-inflammatory cytokines IFN-γ and TNF-α as compared to control tumor-bearing mice, in the brain compartment." (PMID 36949040, 2023). "Anti-tumor immune cells are known to produce an array of cytokines such as TNFα, IFNγ, and CD107 as a measure of their activity." (PMID 36900259, 2023). "We therefore determined if the EMT genes that are most significantly downregulated by Sf3b1K700E in KPC tumours are induced by TNF-α or TGF-β." (PMID 37823551, 2023). "Tumor necrosis factor-α is a multifunctional cytokine important in immune regulation, inflammation, thrombosis, and tumor metastasis." (PMID 37559057, 2023). "Chronic activation of the immune system leads to an accumulation of T- and B-cells that release pro-tumourigenic molecules (e.g., IL-4, IL-10, IL-13, and TNF-α) aiding tumour formation." (PMID 37627054, 2023). "TNFα via NF-kB has been shown to inhibit anti-tumour immune responses of leukocytes and to contribute to tumour cell proliferation, migration, and metastasis." (PMID 37240301, 2023). "TNF-α released by tumor cells promotes the peritumoral adipocytes’ transformation into CAAs, through overexpression of miRNA-130, which decreases the transcription of PPARγ and promotes the adipocytes dedifferentiation by NF-κB pathway activation." (PMID 37760840, 2023). "In particular, TNF-α and IL-6 have garnered considerable attention in the context of cancer, being labeled master regulators of tumor-related inflammation." (PMID 37964946, 2023). "Stimulated by chemotherapy, tumor cells die, releasing more tumor necrosis factor, inducing more inflammatory responses, and more cytokines are secreted into the peripheral nervous system, signaling to the central nervous system." (PMID 37542585, 2023). "Many oncolytic adenoviruses have been used to locally express various cytokine such as IL-2 and tumor necrosis factor α (TNF-α), IL-18, IL-24 or IL-12 in order to potentiate anti-tumor immune responses." (PMID 39086690, 2023). "M1-macrophages exert anti-tumor effects by promoting increased expression and release of cytokines such as IL-1β, TNF-α, IL-6, and IL-12 and elevating the helper T cell 1 (Th1)-mediated immune response." (PMID 37588995, 2023). "Interferon and TGF-β can directly or indirectly inhibit tumor cell growth, TNF and various chemokines play a role by promoting angiogenesis, and IL-18 can activate NF-κB signal, induce cancer cell proliferation and invasion, and prevent cell apoptosis." (PMID 37091857, 2023). "Tumor necrosis factor alpha (TNF-α), un this context, has been shown to have dual role on tumor development." (PMID 37563607, 2023). "After activation, NK cells can directly kill transformed cells or tumor cells by producing perforin and granzyme B or by inducing target cell death through tumor necrosis factor (TNF)-α, Fas ligand (FasL), and TNF-related apoptosis-inducing ligand (TRAIL)." (PMID 38022613, 2023). "Similar to our results, it has been reported that the presence of BM-MSCs decreases TNFα in cocultures even in the presence of LPS, and the same effect has been demonstrated with tumor-derived MSCs." (PMID 37048119, 2023). "TNF-α, one of the most important inflammatory cytokines, was first identified as an anti-tumor cytokine that resulted in tumor necrosis." (PMID 37446321, 2023).
tumor (continued). "TNF-α is a dual acting cytokine with a proinflammatory effect that plays a crucial role in the development of irAEs and with tumor surveillance properties through its induction of apoptotic cell death in a wide variety of tumor cells." (PMID 37958355, 2023). "Among the cytokines involved in the regulation of inflammatory processes and tumor promotion, TNFα plays a key role." (PMID 36769105, 2023). "We analyzed the cytokine milieu of the tumor microenvironment and discovered high levels of the pro-inflammatory cytokines tumor necrosis factor (TNF)-α, interleukin (IL)-1β, and IL-6." (PMID 37461742, 2023). "An especially striking observation was the increase in TNF-α response which points to an increase in tumor apoptosis." (PMID 36902456, 2023). "For instance, in a mouse model for breast cancer, HFD in combination with fish oil resulted in decreased tumor weight and number, accompanied by a decrease in the pro-inflammatory markers TNF-α and IL-6 and an increase in the anti-inflammatory marker IL-10." (PMID 36830818, 2023). "TNFα appeared to work when injected directly into tumours in high doses, however, its severe toxicity, when administrated systemically, almost entirely hampered its usage in cancer therapy." (PMID 36900285, 2023). "TNFα is frequently present in tumours in large quantities, which can be exploited by delivering drugs that sensitise cells to this cytokine." (PMID 36900285, 2023). "Numerous studies highlight NF-κB p65 (RelA) and TNFα mediated exacerbation of inflammation in the tumor microenvironment." (PMID 37892820, 2023). "Upon activation, NK cells mediate tumour killing by releasing perforin and granzyme in addition to triggering apoptosis of tumour cells through secreting TNFα or by membrane-bound activation of TRAIL and FASL pathways." (PMID 39935547, 2023). "Cytokines such as interferon, interleukin and tumor necrosis factor are involved in the regulation of tumor microenvironment and anti-tumor immune response." (PMID 37876934, 2023). "Current preclinical studies and clinical studies have reported an elevated expression of TNF-α in both peripheral blood and the treated tumor within hours after LITs, suggesting systemic and local responses to LITs." (PMID 36831664, 2023). "By KEGG analysis in tumor signal pathways, we found that B cell maker genes were mainly enriched in estrogen response, interferon-gamma response, androgen response, TNF-α signaling via NK-κB, and complement response." (PMID 37889543, 2023). "Scavenger receptor-A (SR-A, CD204) expressed on TAMs and dependent on the presence of TNF-α was found to be involved in tumor cell invasion." (PMID 37298230, 2023). "In particular, TNFα/TNF-R1, FasL/Fas and TRAIL/DR4 or DR5 systems exert pleiotropic effects, associated with both tumor-promoting and tumor-suppressing effects in the tumor microenvironment (TME)." (PMID 37173331, 2023). "At a low concentration (10 ng/mL) TNFα promotes tumor growth, while at a higher concentration (>50 ng/mL), TNF-α reduced the viability of the cells." (PMID 37012245, 2023). "Our experiments further revealed a specific exosomal release of vault RNAs upon tumor cell damage (TNFα-dependent or independent)." (PMID 36980669, 2023). "The AuNPs and TNF‐α plasmids were orally delivered and transported into internal microcirculation via transcytosis and then accumulated at tumor sites." (PMID 39188274, 2023). "Transplantable tumors in mice undergo fast hemorrhagic necrosis through the TNF pathway which also plays a role in cell transformation, survival, proliferation and metastasis stage of tumor growth." (PMID 36608061, 2023). "CAR-T cell targeting of FRβ+ TAMs will result in FRβ− (M1 phenotype) TAMs becoming predominant in the tumour stroma, creating an anti-tumour environment by the release of proinflammatory cytokines such as TNFα." (PMID 39935547, 2023). "This, in turn, can result in tumour immunosuppression, suggesting a potential role for TNF-α in this biological event." (PMID 36980727, 2023).
tumor (continued). "In the case of OC, neutrophils work in tandem with TNF-/IL-17 signaling to promote tumor development and enhance premetastatic niche creation via NETs." (PMID 37298230, 2023). "Observations indicated that IL‐12 increased 10 times, TNF‐α increased 10 times, and tumor‐supporting cytokines decreased by 2 times." (PMID 38455223, 2023). "Other reviews have also indicated that inflammatory cytokines, such as interleukin(IL)-1, IL-6, IL-10, tumor necrosis factor-α, macrophage migration inhibitory factor, and transforming growth factor-β, are involved in tumor initiation and progression." (PMID 36855430, 2023). "All treatment groups showed a tendency to lower TNF-α levels, which was due to the inhibition of tumor growth." (PMID 37033618, 2023). "Exosomes released by tumor cells carried vascular endothelial growth factor (VEGF), transforming growth factor β (TGF-β), and tumor necrosis factor α (TNF-α) to induce vascular formation which is important for tumor growth and metastasis." (PMID 37497408, 2023). "PTT-induced hyperthermia can further stimulate cytokine production such as IFN-γ and TNF-α, which in turn promote the activation and tumor infiltration of T cells." (PMID 37376125, 2023). "We used CRISPR-Cas9 technology to knock out B7-H3 in PC3 and DU145 cells and then verified that B7-H3 CAR-T cells specifically recognize B7-H3 positive target cells and produce cytokines IFN-γ and TNF-α to induce tumor cell lysis in vitro." (PMID 37149721, 2023). "Growing embodies showed that IL1, IL6, and TNFα are critical drivers of tumor growth, progression, and metastatic spread." (PMID 38213319, 2023). "Tumor necrosis factor (TNF-α) is a pleiotropic cytokine involved in the control of inflammation, anti-tumor responses, and maintenance of immune system homeostasis." (PMID 37176100, 2023). "The Tumor Necrosis Factor (TNF) Receptor Super Family (TNFRSF) are potentially excellent targets for modulation which result in specific anti-tumor immune responses." (PMID 37304285, 2023). "Simultaneously, the Se-PC peptide can enter the blood circulation, and irradiation promotes the synthesis of antioxidant enzymes and the immune response by the IL-6/TNF-α pathway to protect normal tissues against tumor metastasis." (PMID 37994159, 2023). "Radiation is also a potent stimulator of TNFα production in the tumor microenvironment, which we previously showed increases the effectiveness of birinapant and AZD1775 as individual agents." (PMID 36831373, 2023). "It is well documented that the presence of cytokines such as IL-1, IL-6, and TNF-α or chemokines such as CCL2 and CXL8 from white blood cells or tumor-associated macrophage (TAMs) generate cancer-related inflammation in tumors." (PMID 36900505, 2023). "M1 macrophages release TNF-α and can promote tumor formation by increasing the inflammatory factor and chemokine transcriptional levels." (PMID 37569777, 2023). "To this end, we cultured WT-GSCs in the absence or presence of TNF-α at 10 ng/mL, a concentration previously demonstrated to promote tumor growth in human GSCs54." (PMID 37012245, 2023). "For instance, HFD-induced obesity leads to CD8+ T cell exhaustion by reducing the production of granzymes and cytokines (IFN-γ and TNF-α), ultimately accelerating tumor growth in mouse models." (PMID 37700339, 2023). "Previous studies have shown that CAFs respond to cytokines (TNF, IL-1β) in the tumor microenvironment to drive their proinflammatory activation." (PMID 38203319, 2023). "This pattern was consistent with the analysis of tumor hallmarks, which showed upregulated expression of TNF and JAK/STAT pathways and downregulated expression of angiogenesis pathway during RCT treatment." (PMID 36710358, 2023). "On the one hand, IL-1β promotes angiogenesis and tumor progression by activating endothelial cells, which produce vascular endothelial growth factor and other proangiogenic factors (e.g., TNF)." (PMID 38248096, 2023).
tumor (continued). "Cytokine analysis of tumor extracts additionally showed that vaccination with ITI-3000 induced significant expression of IFNγ, IL-1β, IL-2, and TNFα, indicative of a strong anti-tumor immune response." (PMID 37711623, 2023). "M2-like macrophages produce ARG1 and other anti-inflammatory factors to promote tumor, while M1-like macrophages produce TNF-α and other pro-inflammatory factors to inhibit tumor." (PMID 38012650, 2023). "Levels of the critical tumor-promoting TNF and IL-6 sera were low, but mucosal-healing IL-22 also supports tumor formation." (PMID 37275854, 2023). "Tumoral cells can express suppressor cytokines (IL-6, IL-10, TFGβ, TNFα), which promote tumor growth and metastasis, suppressor cells (LT reg), and immunosuppressive molecules." (PMID 36830015, 2023). "This suggested that the main role that TNFα, IL-1β, IL-6 played in the tumor was exerted by and on macrophages." (PMID 37461742, 2023). "Understanding the synergistic inhibitory effect exerted by TNF-α and MSCs on tumor cells will be useful in designing future anti-tumor cell therapies." (PMID 36814921, 2023). "Several inflammatory factors related to tumours, including interleukins (IL-6, IL-10, IL-17, IL-1β), TGF-β, IFN-γ, TNF-α, VEGF, and MMPs, are also the cancer-associated genes." (PMID 37742025, 2023). "It has been shown to promote tumor growth in chronic inflammatory diseases, although TNF- α has anti-tumor property." (PMID 37006260, 2023). "These immune cells are known to produce inflammatory cytokines (IFN‐γ and TNF‐α) that can induce IP expression in tumour cells." (PMID 37097039, 2023). "Tumor-associated macrophages are known to suppress adaptive immunity through secretion of variety of chemokines and cytokines such as tumor necrosis factor-α, interleukin (IL)-1, IL-6, and IL-10 to promote tumor growth, angiogenesis, invasion, and migration." (PMID 37408277, 2023). "Conversely, there are reports suggesting the benefits of the potent pro-inflammatory cytokine (TNF-α) in cancer treatments, especially given its recognition as a major factor in the anti-tumor activities of Coley’s toxins." (PMID 38022654, 2023). "TNF was found elevated in the tumor microenvironment of NSCLC patients and was suggested to promote EMT, invasion and metastasis in NSCLC." (PMID 37085672, 2023). "Using qRT‐PCR and ELISA, we demonstrated that proinflammatory, anti‐inflammatory, and tumor‐associated marker expression changed during THP‐1‐derived marcrophage development in vitro, mimicking a TAM‐related profile (e.g., TNFα, IL‐1β)." (PMID 38037545, 2023). "TNF was discovered as a factor inducing the death of tumor cells but was subsequently shown to promote tumor development in different models, such as DMBA/TPA induced skin carcinogenesis and obesity-associated liver cancer." (PMID 36653597, 2023). "This treatment regimen should allow expression of TNFα within the tumor, then administration of CDDP should induce activation of the promoter and further boost TNFα production." (PMID 37331004, 2023). "While the BON tumor model demonstrated significant induction of TNFα upon ASA404 treatment and related high therapeutic responsiveness in vivo, no comparable effects were detectable in the NCI-H295R xenografts." (PMID 36980669, 2023). "Whereas, circulating lymphocytes exhibit effective anti-tumor cellular immune response by secreting various cytokines such as interferon and tumor necrosis factor." (PMID 37165423, 2023). "On the other hand, IL-6 and TNFα are the main molecular mediators of the anti-tumor functions of MCs, with the latter able to directly activate either apoptosis or necroptosis pathways in tumor cells." (PMID 37376140, 2023). "NK cells also produce pro-inflammatory cytokines such as IFNγ and TNFα to promote anti-tumor activity of other immune cells or to directly inhibit tumor cells." (PMID 37277776, 2023).